MUC16 (mucin 16, cell surface associated)
Diseases named in the same sentence as MUC16 in open-access papers (continued):
Sharing a sentence is not in itself a finding about the gene and the disease.
tumor (continued). "We observed a remarkable proportion of MUC16 (+) patients with surgically resected CCA as 57 of 168 (34%) patients with CCA had evidence of MUC16 expression in tumor tissue." (PMID 36230626, 2022). "For instance, MUC16-redirected CAR T cells exhibited a therapeutic benefit versus human breast OVCAR-3 tumor-bearing mice and also prolonged their survival time." (PMID 35093187, 2022). "CA125/MUC16 was originally used as a biomarker for ovarian cancer given its high expression in tumor cells, and elevated levels in the sera of patients with ovarian cancer." (PMID 35326701, 2022). "Top 10 candidates also included proteins associated with tumor progression (LAMA5, SDCBP, TENA, PTPRJ, MUC16, TAOK1; see “Discussion”)." (PMID 35241737, 2022). "Second, the correlation tests revealed a significant positive association between the concentrations of CA125 (MUC16), STAT3, pSTAT3, and IL-17; their synergic activities were linked to the Tumor Node Metastasis (TNM) stage." (PMID 36552994, 2022). "It is possible that 22A31 interrupts the heterotypic interaction between ERC/mesothelin and other molecules such as CA125/MUC16 on the surface of tumor cells or adjacent stromal cells, leading to the suppression of proliferative activities of carcinoma cells." (PMID 35565327, 2022). "There was a significant association between high MUC16 expression in a cohort of 116 PDAC patients and altered receptor-tyrosine kinase (RTK) pathways, a highly upregulated and tumor-promoting mechanism in this cancer." (PMID 35628269, 2022). "The tumor mutational burden (TMB) has recently been recognized as a biomarker for predicting prognosis and response to immune checkpoint inhibitors, while mucin 16, cell surface associated (MUC16) is frequently mutated in GC." (PMID 35211490, 2022). "PET imaging showed high tumor uptake in MUC16-positive xenografts as seen in the maximum intensity projection images of the NOD-SCID mice at 24–120 h p.i.." (PMID 36559316, 2022). "These regions contained tumor-related genes, such as Muc16, Pik3, and Bcl2 in amplification regions and Hras, Notch1, Apc2, Ccnd1, Batf2, Dapk3, Smarca4, Traf2, Traf3, Cdk3, and Cdh4 in deletion regions." (PMID 36424557, 2022). "Previous studies indicated that the mutation number of MUC16 was closely correlated with tumor mutational burden (TMB), and the high mutation number of MUC16 was correlated with better overall survival (OS)." (PMID 36291742, 2022). "While MUC16 and TTN genes mutation were previously reported to correlate with prognosis, tumor mutation burden, and immunotherapy efficacy in cancers." (PMID 36685901, 2022). "This article will review the mechanism of MUC16 in tumor genesis and progression, and focus on the research actuality of MUC16 in tumor therapy." (PMID 35899441, 2022). "MUC16/CA125, a commonly used blood biomarker of ovarian cancer, is associated with cancer proliferation in several tumor entities." (PMID 36230626, 2022). "MUC16 plays an important role in tumor genesis, proliferation, migration, invasion, and tumor immunity through various signaling pathways." (PMID 35899441, 2022). "Intraperitoneal delivery of the virus by Ad5/MUC16-1040/TK-EGFP-infected OVCAR4 cells used as a carrier also suppressed tumor cell growth and prolonged mouse survival." (PMID 34503075, 2021). "A possible mechanism for this is that MUC16 binds to the Siglec 9 receptor on NK cells, downregulating their cytotoxicity and thereby allowing tumor cells to escape immune surveillance." (PMID 34212175, 2021). "Circ_MUC16 was a circRNA that was highly expressed in tumor tissues relative to matched normal tissues." (PMID 34837947, 2021). "Inhibiting MUC16 has been found to inhibit of tumour progression and enhance the effect of immunotherapy." (PMID 33543559, 2021).
tumor (continued). "MUC16 and mesothelin interactions are thought to provide the first step in tumor cell invasion of the peritoneum." (PMID 34150633, 2021). "The probe was able to achieve tumor visualization with low background, indicating the potential of MUC16 for imaging." (PMID 34522225, 2021). "CAR-T cells were modified in order to express the MUC-16 ectodomain and IL-12, which enhances cytotoxicity, persistence, and modulation of the tumor microenvironment." (PMID 33391401, 2021). "MUC16 is known to bind mesothelin, a cell surface protein expressed by tumor cells and the mesothelial lining which facilitates metastasis." (PMID 33391401, 2021). "MUC16 was capable of binding the tumour necrosis factor–related apoptosis‐inducing ligand, thereby inhibiting apoptosis of tumour cells." (PMID 33543559, 2021). "Minimal targeting to T-cell-rich organs, such as the spleen, was observed with a bispecific harboring a weak CD3 arm, which mainly targeted the MUC16 + tumor." (PMID 34257348, 2021). "The MSLN–MUC16 interaction has been shown to be important for tumor cell adhesion and metastasis, as MSLN can bind MUC16 on other tumor cells." (PMID 34439085, 2021). "Since MUC16 is expressed on the tumor cell surface and is also shed, it is also a good candidate for regulating immune cell interactions." (PMID 33922973, 2021). "Upon binding, this monoclonal antibody elicits antibody-dependent cellular cytotoxicity (ADCC) and inhibits the adhesion of MSLN-expressing tumor cells to MUC16-expressing tumor cells." (PMID 34439085, 2021). "Stimulatingly, MUC16 has been shown to be altered only in gynecological malignancies and other benign conditions and has been recognized as a tumor biomarker and a novel target for cancer therapy." (PMID 34209172, 2021). "These cell lines, with forced expression of the terminal amino acid sequence of the C-terminal MUC16 ectodomain, contain the N-glycosylation sites that drive tumor growth and invasion." (PMID 33580170, 2021). "In this context, it is of note that several RCC studies reported an association between increased levels of MUC16, poor prognosis and advanced tumour stage, suggesting the potential use of MUC16 as a serum biomarker in RCC." (PMID 33946379, 2021). "In contrast, a bsAb harboring a CD3 arm with a higher affinity to CD3 targeted both T-cell-rich organs and the MUC16 + tumor." (PMID 34257348, 2021). "Particularly for P4, the shared mutations included several important tumor metastasis–related and drug-resistance genes, such as ZNF143, MUC16, NUMA1, ADAMTS2, and MOV10." (PMID 34616428, 2021). "MUC16-CAR-T cells injected intravenously or intraperitoneally are able to delay OC’s progression or altogether remove tumours in mouse tumour-bearing models." (PMID 33800608, 2021). "We monitored the tumor burden and serum cytokines in mouse models of solid (MUC16-expressing) or hematologic (BCMA-expressing) malignancies following treatment with CD3-based bsAbs engineered with different CD3 affinities." (PMID 34257348, 2021). "For tumor growth, we discovered that circ_MUC16 knockdown notably inhibited tumor volume and tumor weight, and Propofol treatment further weakened tumor volume and tumor weight in sh-circ_MUC16-infected group compared to sh-NC-infected group." (PMID 34837947, 2021). "For example, MUC16 inhibited cytolysis via human NK cells as well as the formation of NK-tumor conjugates." (PMID 33679883, 2021).
tumor (continued). "The MUC16xCD3M bsAb accumulated in both the spleen and MUC16-expressing tumor, suggesting recognition of CD3-positive T cells in the lymphoid tissue and MUC16 on the tumor cells." (PMID 34257348, 2021). "The tumor immune microenvironment with dual-positive CD8A and PD-L1 was overrepresented in MUC16-mutated tumors compared with wild-type ones (43.8% vs 32.4%; odds ratio, 1.63; 95% CI, 1.46-1.80; P < .001)." (PMID 32845327, 2020). "We were able to confirm the increased mRNA expression of COL11A1 and MUC16 in samples from LUAC patients compared with non-tumor lung tissue samples from the same patient." (PMID 32707902, 2020). "Binding between the membrane bound form of MUC16 and Siglec-9 prevents the formation of an immunological synapse between tumour cells and NK cells, thereby preventing the cytotoxic activity of NK cells." (PMID 32937961, 2020). "The tumor promoting factors MUC16, MACC1 and GRHL2 were downregulated in PitNETs after SSA/DA therapy and in GH3 cell following octreotide treatment." (PMID 33680922, 2020). "Similar to MUC1, Siglec9 can interact with MUC16 expressed on epithelial ovarian cancer cells, protecting tumour cells from immune attacking." (PMID 32322597, 2020). "The three cell lines showed positive staining for CA 19-9, MUC1 and MUC16, with moderate to strong (2+ to 3+) intensity in more than 80% of tumor cells, with the exception of CA 19-9, which was only expressed in 20% of PUC-GBC2 cells." (PMID 32293552, 2020). "In an in vitro experiment, the authors used cell proliferation assays with NIH:OVCAR3 (MUC16 knockdown) and SKOV3 (MUC-16-expressing) cells to investigate the tumour initiation capacity of MUC16 knockout cell lines." (PMID 33322519, 2020). "The cytoplasmic tail of MUC16 plays an essential role in tumour growth; in fact, the deletion of the MUC16 C-terminal domain (CTD) inhibits tumour proliferation, cell motility, and invasiveness." (PMID 33322519, 2020). "Three tumor development promoting factors MUC16, MACC1, and GRHL2, were significantly downregulated in therapy administered PitNET tissue; this finding was supported by functional studies in GH3 cells." (PMID 33680922, 2020). "Based on low overall normal tissue and relatively high tumor expression, MUC16 appears to be an ideal TAA; however, isolating high-affinity CTLs that recognize non-mutated MUC16 epitopes has proven elusive." (PMID 33087697, 2020). "Subsequently, their results showed that cell surface MUC16 down-regulation results in the arrest of tumour cell growth in vitro." (PMID 33322519, 2020). "CA125 is a cleavage peptide of MUC16, which is a member of the mucin family of glycoproteins that is often used as a tumor marker." (PMID 33376560, 2020). "Our study discovered that patients with MUC16 mutations had significantly high TML, immune-activated tumor microenvironment and favorable survival outcome." (PMID 32491995, 2020). "In the present study, we demonstrate for the first time that HGSOC ascites, a highly inflammatory tumor environment, markedly up-regulates the expression of MUC16 glycoprotein in primary HPMCs and stimulate its release from the cell surface." (PMID 31039761, 2019). "MUC16 overexpression has been reported in human OvCa, where it plays an important role in tumor proliferation, drug resistance, and immune evasion." (PMID 31783651, 2019). "The ectodomain of MUC16 can be cleaved and released in circulation, the detection of which in serum is frequently performed for tumor diagnosis." (PMID 31783651, 2019). "Others have confirmed these data by showing that MUC16 knockdown in overexpressing breast or pancreatic cancer cell lines decreased cell proliferation and in vivo tumor growth." (PMID 31039761, 2019).
tumor (continued). "In contrast, TNFα and IFNγ stimulated MUC16 mRNA levels in tumor cells, a process that was, at least partly, NF-κB dependent." (PMID 31039761, 2019). "It is well known that MUC16 is highly expressed on malignant cells and not on healthy cells and therefore the NanoComposite can impede tumor growth and even halt metastasis based on the binding to MUC16." (PMID 30287783, 2018). "MUC16, which is cleaved and shed into the bloodstream, is actively researched as a serum biomarker for a variety of tumor types." (PMID 29552305, 2018). "In the 23 SOCs previously studied by us, MUC16 expression was observed in 23/23 (100%) tumours, MUC1 in 20/23 (87.0%), and truncated O-glycans expression was present in 18/23 (78.3%) for Tn, 21/23 (91.3%) for STn, and 20/23 (87.0%) for T." (PMID 30011875, 2018). "Localization of 89Zr-MUC16-CD3low and 89Zr-MUC16-CD3high was next measured in tumor-free MUC16 and CD3 double humanized immunocompetent mice." (PMID 30400822, 2018). "Investigation of candidate targets has focused on cell membrane antigens such as MUC1, CD44v6, MUC4, MUC16 (CA-125), and other tumor-specific markers that are relatively specific for CSC populations." (PMID 29796189, 2018). "At the study end point, the average tumor growth inhibition levels of FSH-MUC16.1-G-NP, MUC16.1-G-NP and FSH-G-NP were 51.8%, 24.7% and 40.8%, respectively." (PMID 29542355, 2018). "The notable reduction in tumor size and mouse weights corresponded with decreased MUC16/CA125 antigen expression levels determined with the ELISA technique." (PMID 30287783, 2018). "Here we report the effects of tumor-shed antigen CA125/MUC16 on suppressing IgG1-mediated antibody-dependent cellular cytotoxicity (ADCC)." (PMID 28881712, 2017). "Our data are consistent with our recent findings that overexpression of MUC16 C-terminal domain resulted in significantly higher tumor growth and metastatic burden towards diaphragm and peritoneum." (PMID 27382435, 2016). "Overexpression and shedding of MUC16 is predicted to contribute to immunosuppressive activities further protecting tumor cells from host immune responses." (PMID 26918940, 2016). "Our results together with accumulating evidence about the interaction between tumor-cell glycoprotein such as mucin MUC16 and lectin, galectin-3 for instance in PDAC will pave new ways to interfere with cancer progression." (PMID 27382435, 2016). "We suggest that elevated MUC16, in turn, protects the tumor against the immune system and cytotoxic drug penetration." (PMID 26918940, 2016). "MUC16 has been used as a tumor marker for over thirty years due to its overexpression in ovarian and other cancers, yet little is known about its regulation." (PMID 26918940, 2016). "MUC16 knockdown cells show a significant reduction in tumor formation and metastasis in immunocompromised mice." (PMID 27382435, 2016). "We were therefore encouraged to see that Meso64-TR3's binding affinity to the MUC16 biomarker was not only retained but resulted in a much more potent cancer drug compared to its full length predecessor on MUC16-positive tumor cells." (PMID 27120790, 2016). "Further, it has also been observed that with similar tumor size, the number of metastasis to other internal organs is reduced in MUC16 knockdown cells." (PMID 27382435, 2016). "MUC16 (also known as the serum tumor marker, CA 125) is the largest transmembrane mucin being 2–5 MDa including O-linked and N-linked glycosylation." (PMID 26918940, 2016). "The purpose of these studies was to determine if relative MUC16 expression correlated with TNFα or IFNγ expression, independently of tumor stage or grade." (PMID 26918940, 2016).
tumor (continued). "A quantitative analysis of receptor-ligand binding kinetics of functional selectin ligands expressed by metastatic tumor cells, such as MUC16 and PODXL, in the presence of shear flow will further the understanding of the metastatic process." (PMID 26329844, 2015). "We observed similar metabolic alterations that correlated with MUC16 expression in primary tumor tissue specimens from human pancreatic adenocarcinoma cancer patients." (PMID 26046375, 2015). "Since the in vitro transformation data were very compelling for short carboxy-terminal elements of MUC16, the effect of expression of the carboxy-terminal elements in transgenic mice and the rate of spontaneous tumor formation was examined." (PMID 25965947, 2015). "These genes included tumor markers (MUC16), genes that control tumor migration (MYL9), metastasis (CEACAM6, VEGFC, CX3CL1, CST1, CCL5, S100A9, IGF1, NOTCH3), cell adhesion (FN1, CEACAM1), and inflammation (TRAF2, NF-κB2 and RelB)." (PMID 26090868, 2015). "As few as 114 amino acids from the carboxy-terminal portion of MUC16 were sufficient to increase soft agar growth, promote matrigel invasion, and increase the rate of tumor growth in athymic nude mice." (PMID 25965947, 2015). "A significantly higher tumor growth and metastasis were observed in mice implanted with cells expressing MUC16-Cter as measured by the total luciferase flux (photons/sec)." (PMID 25691062, 2015). "In order to measure the effects of MUC16 on tumor growth rate, we selected a flank tumor model to facilitate regular tumor measurements." (PMID 25965947, 2015). "In our current study, we characterized a tumor-targeted variant of TR3 by harnessing the strong binding affinity of the two well described biomarkers mesothelin and MUC16." (PMID 24447304, 2014). "As a result, tumor cells surviving NK cell attack are high expressors of MUC16 that are more resistant to immune attack." (PMID 24886523, 2014). "Another important aspect of the mesothelin/MUC16 interaction is its contribution to both homotypic (tumor cell-tumor cell) and heterotypic (tumor cell-mesothelial cell) cell interactions." (PMID 24447304, 2014). "Expression of MUC16CTD in malignant cells enhances migration, invasion, tumor growth and metastasis whereas MUC16 knockdown completely abolishes tumor formation in vitro and in vivo." (PMID 24690311, 2014). "We found that cells positive for the MUC16 tumor marker were heavily coated with Meso-TR3, while cells with nearly undetectable antigen expression were incapable of capturing Meso-TR3 and stained only weakly for the targeted drug (arrow)." (PMID 24447304, 2014). "Innate immune cells, Natural Killer (NK) cells and monocytes are unable to attack tumor cells expressing high levels of MUC16." (PMID 24886523, 2014). "MUC16 is cleaved and shed into the bloodstream and has been the focus of active research as a biomarker in the serum for a variety of tumor types." (PMID 22066010, 2011). "CA125/MUC16 is a tumor biomarker that is currently used for the follow-up of patients with ovarian cancer." (PMID 22066010, 2011). "MUC16 expression appears to be stronger in metastatic lesions when compared to the primary tumor, suggesting a role in PC metastasis." (PMID 22066010, 2011). "Our recent work shows that the anti-adhesive property of MUC16 allows the tumor cells to circumvent immune synapse formation with cytotoxic NK cells." (PMID 20497550, 2010). "Recent studies though have shown that the expression of mucin (MUC) molecules on the ovarian cancer cell surface, namely, MUC16 which is a carrier for the CA125 tumor marker, assist in the avoidance of the tumor cells' recognition by NK cells." (PMID 21318181, 2010). "Tumor cells secrete MUC16 into the peritoneal fluid (PF) and from the abdominal cavity this mucin leaks into the blood stream and can then be detected via the CA125 serum assay." (PMID 20350313, 2010).